METTL14 (methyltransferase 14, N6-adenosine-methyltransferase non-catalytic subunit)
Diseases named in the same sentence as METTL14 in open-access papers (continued):
Sharing a sentence is not in itself a finding about the gene and the disease.
breast cancer (continued). "METTL14 expression level is down-regulated in breast cancer, in turn to promote tumor growth, angiogenesis and tumor occurrence and development." (PMID 33552994, 2020). "On the other hand, METTL14 expression is downregulated in glioblastoma, breast carcinoma, endometrial cancer, and bladder cancer cells and tissues." (PMID 33552994, 2020). "In addition, the endogenous interaction of PAK5 with METTL14 was demonstrated in SK-BR-3 breast cancer cells." (PMID 40258843, 2025). "Moreover, combined inhibition of METTL3/METTL14 with paclitaxel (PTX) demonstrated potent synergistic antitumor effects in breast cancer cells and xenograft models." (PMID 41164187, 2025). "While METTL3 and METTL14 have been often reported to be upregulated in breast cancer in previous studies, METTL14 was found to be downregulated in the SCAN-B cohort, a trend that is also prevalently observed in The Cancer Genome Atlas (TCGA) cohort when METTL14 is altered." (PMID 40918643, 2025). "Conversely, in HER2-positive breast cancer (BC), METTL14 inhibits ferroptosis." (PMID 40271153, 2025). "The downregulated METTL14 acts as a tumor suppressor in breast cancer and predicts poor prognosis." (PMID 39457524, 2024). "In addition, the expression of LNC942 was upregulated in breast cancer cells, accompanied by elevated mRNA stability and increased protein expression of METTL14." (PMID 37961996, 2024). "In breast cancer, METTL14 is significantly upregulated in breast cancer tumour tissue." (PMID 38263865, 2024). "However, another study has indicated that m6A modification of lncDBET by METTL14 is important for its overexpression in breast cancer, and subsequently targeting PPAR signaling pathway to promote lipid metabolism via directly targeting FABP5." (PMID 38075202, 2024). "Importantly, knocking out METTL3/METTL14 sensitizes breast cancer cells to ER stress-inducing drugs." (PMID 39085650, 2024). "Several studies have demonstrated reduced METTL14 expression in breast cancer tissues." (PMID 35115038, 2022). "Mettl14 promotes breast cancer development by regulating m6A and hsa‐miR‐146a‐5p." (PMID 33706799, 2021). "It has been suggested that METTL14 plays an oncogenic role in breast cancer." (PMID 34315512, 2021). "Similarly, m6A methyltransferase METTL14 has been demonstrated to be significantly increased in breast cancer tissues with the function of reshaping miRNA profile of cancer cell lines." (PMID 35004679, 2021). "Mettl14 and m6A levels were upregulated in breast cancer tissues." (PMID 33706799, 2021). "For example, Mettl14 positively modulates m6A modification in breast cancer cells." (PMID 33706799, 2021). "Furthermore, evidence has shown that overexpression of METTL14 in the ER- and PR-negative breast cancer cell line MDA-MB-231 inhibits its proliferation and migration ability." (PMID 33134390, 2020). "Furthermore, mining of TIMER database based on TCGA breast cancer samples demonstrated that only the mRNA expression levels of METTL14 and ZC3H13 were also lower in tumor samples, and there was not any difference of METTL3 and RBM15B." (PMID 33363011, 2020). "Thus, further research is needed to better understand the expression and function of METTL14 in breast cancer." (PMID 33134390, 2020). "Our findings showing that METTL14 expression was the lowest in TNBC compared with other subtypes of breast cancer suggests that it may be worth targeting this protein in the treatment of patients with TNBC." (PMID 33134390, 2020). "Besides, we also calculated the association between immune infiltrates and somatic CNV of METTL14 and ZC3H13 in breast cancer, and these immune cells showed diverse enrichment trends in different CNV types across different types of breast cancer." (PMID 33363011, 2020). "Based on the correlation of APC and METTL14, ZC3H13 in breast cancer, we speculated that METTL14 and ZC3H13 were indirectly involved in mediating tumor immune responses." (PMID 33363011, 2020).
breast cancer (continued). "Since such tumors are known to be more aggressive and to have a poor prognosis, this finding indicates that the downregulation of METTL14 expression may be closely related to highly invasive breast cancer and a poor prognosis." (PMID 33134390, 2020). "Interestingly, a similar study showed that the overexpression of METTL14 inhibits cell viability and colony formation in breast cancer." (PMID 33292526, 2020). "Furthermore, METTL14 exhibits substantial regulatory impacts within breast cancer cells." (PMID 39972939, 2025). "However, the role of METTL14 in breast cancer remains controversial." (PMID 39563370, 2024). "However, m6A modification of miRNA mediated by METTL14 regulates the malignant progression of breast cancer remains unclear." (PMID 38263865, 2024). "In HER2-positive breast cancer, elevated expression of PAK5 promotes m6A modification of lncRNA MALAT1 through phosphorylation of the methyltransferase METTL14, thereby stabilizing MALAT1 RNA level." (PMID 40258843, 2025). "In breast cancer cells, endoplasmic reticulum (ER) stress induces XBP1s-dependent transcriptional activation of METTL3/METTL14, thereby elevating cellular m6A levels." (PMID 41164187, 2025). "Reduced activity of METTL14 and ZC3H13 methyltransferases correlates with lower survival and acts as a tumor-suppressive in breast cancer." (PMID 41157107, 2025). "In HER2-positive breast cancer, elevated expression of PAK5 promotes m6A modification of lncRNA MALAT1 through phosphorylation of the methyltransferase METTL14 at serine 399, thereby stabilizing MALAT1 RNA level." (PMID 40258843, 2025). "Numerous studies have demonstrated that m6A regulatory factors, including METTL3, METTL14, and ALKBH5, play pivotal roles in breast cancer cells, affecting cell proliferation, metastasis, and drug resistance." (PMID 39972939, 2025). "Targeting regulators such as METTL3, METTL14, IGF2BP3, or YTHDF1 can alleviate T-cell suppression in melanoma, colorectal cancer, non-small cell lung cancer (NSCLC), and breast cancer." (PMID 39372415, 2024). "Mechanistically, the upregulation of METTL14 was observed upon the overexpression of LNC942, whereas the downregulation of METTL14 was observed upon the knockdown of LNC942 in breast cancer cells." (PMID 37961996, 2024). "To explore the mechanisms by which METTL14-mediated m6A modification regulates breast cancer stemness, we performed methylated RNA immunoprecipitation (MeRIP) sequencing using MCF7 cells, in which METTL14 is highly expressed." (PMID 39563370, 2024). "In breast cancer, METTL14 and ZC3H13 were down-regulated, indicating a positive correlation between the expression of METTL14 and ZC3H13 positively correlated with various kinds of immune cells, including macrophages, T cells and DCs." (PMID 38637813, 2024). "Our analysis of proteomic data from breast cancer, sourced from CPTAC and TCGA, demonstrated that METTL14 is consistently and significantly downregulated in TNBC, aligning with the observed decrease in m6A levels." (PMID 39563370, 2024). "METTL14, required for the catalytic activity of METTL3, was also upregulated in the breast cancer cell lines." (PMID 36725888, 2023). "It has been reported that METTL14 and ZC3H13 act as tumour suppressor genes and predict poor prognosis in breast cancer." (PMID 36567510, 2023). "Accumulating data indicate that METTL14 as a m6A “writer” shows a decreased expression in CRC, bladder cancer and breast cancer, but an increased level in thyroid and pancreatic cancers." (PMID 35164771, 2022). "In breast cancer (BC), the low METTL14 level was correlated with a poor prognosis, and its abnormal expression could promote the invasion of BC by affecting the tumor progression-related pathways and mediating the immunosuppression." (PMID 36371254, 2022).
breast cancer (continued). "For example, m6A modification mediated by the cooperation of METTL14, ALKBH5, and YTHDF3 was reported to influence the cell cycle, induce the progression of EMT, and contribute to angiogenesis of cancer cells in breast cancer." (PMID 34996459, 2022). "METTL14 stabilizes METTL3 and recognizes target RNA, which is found to be an oncogene or a tumor suppressor gene in breast cancer." (PMID 35721510, 2022). "It has been shown that METTL14 acts as a tumor suppressor in colorectal cancer (CRC), bladder cancer and breast cancer, but represents an oncogenic factor in thyroid cancer, pancreatic cancer and leukemogenesis." (PMID 35164771, 2022). "Low expression of METTL3, METTL14, WTAP and FTO was shown to correlate with relapse-free survival in breast cancer." (PMID 35721510, 2022). "Another study based on bioinformatics suggests that the low expression of METTL14 and ZC3H13 mRNA indicates a poor prognosis of breast cancer." (PMID 33777035, 2021). "Our previous study supports the overexpression of m6A writer METTL14 by LNC942 regulation, which depends on a direct binding pattern and is involved in breast cancer proliferation and progression." (PMID 34743750, 2021). "LNC942 directly recruited METTL14 protein through specific recognition sites, thus enhancing the expression of downstream target genes CXCR4 and CYP1B1 and promoting breast cancer cell proliferation." (PMID 34336856, 2021). "The expression of METTL14 and ZC3H13 in breast cancer was positively correlated with the infiltration of CD4+T cells, CD8+T cells, neutrophils, macrophages and DC, and negatively correlated with Treg cells." (PMID 33777035, 2021). "In this study, the expression of m6A “writers” METTL3, METTL14, and “erasers” FTO were downregulated in 112 tumor samples compared to the paired normal controls based on TCGA breast cancer dataset." (PMID 34804948, 2021). "Among them, the expression of RBM15, VIRMA, HNRNPA2B1, and YTHDF1/2/3 were significantly upregulated, but METTL3, METTL14, METTL16, WTAP, FTO, YTHDC1, and EIF3A had lower expression in breast cancer compared to normal samples." (PMID 34804948, 2021). "These breast cancer patients with distinct molecular subtypes all represented lower expression of FTO, METTL3, and METTL14, and higher expression of YTHDF1 and YTHDF3 in tumor compared to the corresponding adjacent samples." (PMID 34804948, 2021). "For example, hypoxia can alter the level/activity of METTL14, ALKBH5, and YTHDF3, leading to decreased m6A modification in the target transcripts in breast cancer cells." (PMID 34094986, 2021). "We evaluated the genomic alteration of METTL14 and ZC3H13 among breast cancer samples by the cBioPortal online database (TCGA, PanCancer Atlas)." (PMID 33363011, 2020). "Low expression of METTL14 and ZC3H13 was related to breast cancer progression (increased SBR grade status and NPI classification) and was significantly decreased in ER-, PR- and basal-like, TNBC patients." (PMID 33363011, 2020). "In total, we highlighted the important role of METTL14 and ZC3H13 in breast cancer, provided promising markers for predicting prognosis of patients, and explained the potential molecular mechanism of the two as tumor suppressor genes." (PMID 33363011, 2020). "This study demonstrated that down-regulation of METTL14 and ZC3H13 which act as two tumor suppressor genes was found in breast cancer and predicted poor prognosis." (PMID 33363011, 2020). "This indicated that low expression of METTL14 and ZC3H13 promoted immunosuppression in the breast cancer, which is also an important downstream mechanism for their role in the progression and metastasis of breast cancer." (PMID 33363011, 2020). "In this study, by analyzing the prognostic role of m6A modulators (METTL3, METTL14, WTAP, FTO, and ALKBH5) in breast cancer using on-line databases, we found that only METTL3 played an important role in TNBC metastasis." (PMID 32766145, 2020).
breast cancer (continued). "In order to explore the roles of METTL14 and ZC3H13 in the survival of breast cancer patients, the Kaplan–Meier plotter was used to calculate the correlation between the mRNA expression levels and survival." (PMID 33363011, 2020). "Next, the effects of METTL3, METTL14, and FTO on distant metastasis free survival (DMFS) of total breast cancer patients and TNBC patients were analyzed using KM-plotter on-line database, respectively." (PMID 32766145, 2020). "Aberrant expression of m6A regulators, including METTL3, METTL14, WTAP, ALKBH5, and FTO, has been identified in breast cancer, as well as their potential prognostic values." (PMID 33585234, 2020). "The results showed that METTL14 and ZC3H13 were the down-regulated m6A methylation transferases in breast cancer." (PMID 33363011, 2020). "In addition, the “writers” METTL3 and METTL14 were more predisposed to mutation or CNV than the other genes in ccRCC, while alterations of the “erasers” FTO and ALKBH5 were proved to be more important in breast cancer, glioblastoma and hematological malignancies." (PMID 30877265, 2019). "METTL14 depletion was also shown not only to enhance cell resistance to highly active agents used in the treatment of advanced breast cancer (i.e., paclitaxel and doxorubicin) but also to confer radioprotective effects on ALDH+ breast cancer stem cells." (PMID 41369374, 2025). "Besides breast cancer, overexpression of LncRNA UCA1 also accelerated Acute myeloid leukemia (AML) development by regulating METTL14-mediated CXCR4 and CYP1B1 mRNA." (PMID 37365581, 2023). "On the contrary, another study reported that not only METTL3 but also other members of the writer complex such as METTL14 and WTAP are downregulated in breast cancer, suggesting that lower levels of m6A may contribute to breast tumorigenesis." (PMID 36725888, 2023). "In breast cancer, the expression levels of METTL14 have a positive correlation with the infiltration of CD4+ T cells, CD8+ T cells, dendritic cells, macrophages and neutrophils, but they negatively correlated with Treg cells in breast cancer." (PMID 36407103, 2022). "Furthermore, ZC3H13, METTL14 and APC expression levels were positively related with the number of infiltrating immune cells in breast cancer." (PMID 35721510, 2022). "Downregulation of METTL14 predicts a poor prognosis in patients with CRC and breast cancer." (PMID 35164771, 2022). "Immune infiltration analysis indicated that METTL14 and ZC3H13 could facilitate breast cancer invasion by influencing immunosuppression-related pathways." (PMID 36261786, 2022). "For instance, the expression of METTL14 and ZC3H13 is positively correlated with infiltrating levels of CD4+ T cells, CD8+ T cells, and DCs, but negatively correlated with those of Tregs in breast cancer." (PMID 34616742, 2021). "Several members of m6A writer complexes and readers exhibited 1% mutation frequency, while main methyltransferases (METTL3, METTL14) and demethylases (FTO, ALKHB5) did not mutate in breast cancer samples." (PMID 34804948, 2021). "Furthermore, the deceased patients had relatively reduced expression of FTO, METTL3, and METTL14 in tumor tissues, and increased levels of YTHDF1 and YTHDF3 than the alive patients who were diagnosed with breast cancer at the same period." (PMID 34804948, 2021). "Furthermore, METTL14-mediated m6A methylation modifications of LNC942 promote proliferation and progression in breast cancer cells." (PMID 34178697, 2021). "However, since the expressions of METTL14 and ZC3H13 in breast cancer were significantly reduced, this process is reversed, resulting in a decrease in the stability of APC mRNA and inhibiting the protein level of APC." (PMID 33363011, 2020). "In this study, we used a series of bioinformatic databases and tools to jointly analyze the expression of m6A methylation transferases (METTL3, METTL14, WTAP, RBM15, RBM15B and ZC3H13) and investigate the prognostic value of METTL14 and ZC3H13 in breast cancer." (PMID 33363011, 2020).
breast cancer (continued). "In this study, we used Oncomine and The Cancer Genome Atlas (TCGA) databases to jointly analyze the expression of m6A “writer” in breast cancer including METTL3, METTL14, WTAP, RBM15, RBM15B, and ZC3H13, indicating that the mRNA expression levels of METTL14 and ZC3H13 were lower in tumor samples." (PMID 33363011, 2020). "Survival analysis of METTL14, ZC3H13 and APC in breast cancer patients (the PrognoScan)." (PMID 33363011, 2020). "What is more, survival analysis showed that low METTL14 and ZC3H13 expression could demonstrate poor prognosis in breast cancer for OS and RFS." (PMID 33363011, 2020). "Survival outcome analysis suggested that abnormally low expression of METTL14 and ZC3H13 could predict unfavorable prognosis in four breast cancer subtypes." (PMID 33363011, 2020). "However, the roles of METTL14 and METTL3 in breast cancer, in general, are controversial." (PMID 38545841, 2024). "Mechanistically, LNC942 directly recruits METTL14 protein by harboring the specific recognize sequence (+ 176- + 265), thereby stabilizing the CXCR4 and CYP1B1 mRNA in an m6A modification dependent manner thus finally promoting cell proliferation and colony formation of breast cancer cells." (PMID 37365581, 2023). "Interestingly, METTL14 can enhance DROSHA mRNA stability by catalyzing the m6A modification, indicating that targeting the METTL14-DROSHA-β-Catenin axis might impair breast cancer progression." (PMID 34315512, 2021). "METTL14 knockdown in MCF7 cells also resulted in the upregulation of YAP1, mirroring the response observed in TNBC, suggesting that the underlying molecular mechanism is consistent across various breast cancer subtypes, irrespective of the Hippo pathway activity." (PMID 39563370, 2024). "While our initial focus was on the differences between luminal breast cancer and MSL TNBC, this does not mean that the role of METTL14 in determining YAP1 expression is opposite in these two breast cancer subtypes." (PMID 39563370, 2024). "The expression of METTL3, METTL14, RBM15B, and ZC3H13, but not of WTAP and RBM15, was significantly decreased in breast cancer." (PMID 33363011, 2020). "No increases in METTL3, METTL14 and WTAP protein levels were detected in VIRMA FL-transduced HS578T cells that already express high levels of endogenous full-length VIRMA or in breast cancer cells overexpressing VIRMA N-term compared to control cells." (PMID 37208522, 2023). "Previous studies have reported that METTL14 forms a negative feedback loop with ALKBH5/TFEB in cardiomyocytes treated with hypoxia/reoxygenation and constitutes a positive one with ALKBH5/HuR in breast cancer." (PMID 36288387, 2022). "METTL14, ZC3H13, and APC expression levels had significant positive correlation with infiltrating levels of CD4+ T cells, CD8+ T cells, neutrophils, macrophages, and dendritic cells, and negative correlation with Treg cells in breast cancer." (PMID 33363011, 2020).